PIN1 (peptidylprolyl cis/trans isomerase, NIMA-interacting 1)
Diseases named in the same sentence as PIN1 in open-access papers (continued):
Sharing a sentence is not in itself a finding about the gene and the disease.
nasopharyngeal carcinoma (12 papers, 2013 to 2024). A carcinoma arising from the nasopharyngeal epithelium. "Contrasting evidence has been reported for the −667C variant in the PIN1 promoter, which was found to associate with a low risk of developing nasopharyngeal carcinoma, but a high risk for oral squamous cell carcinoma and HCC." (PMID 30723410, 2018). "We evaluated the association between the risk of nasopharyngeal carcinoma and haplotypes constructed from the two PIN1 polymorphisms (-842G > C, -677C > T)." (PMID 28676695, 2017). "Our previous work reported the association between two single nucleotide polymorphisms (SNPs) in PIN1 promoter and nasopharyngeal carcinoma (NPC) risk with a small sample size in a low incidence area." (PMID 28676695, 2017). "Hyperactivated PIN1 has been shown to cause nasopharyngeal carcinoma." (PMID 39202474, 2024). "However, PIN1 haplotypes analysis in our study indicated that both -842G-667T and -842C-667C haplotype showed an increased risk of nasopharyngeal carcinoma compared to the -842G-667C haplotype." (PMID 28676695, 2017). "In the nasopharyngeal carcinoma model created by PIN1 induction, juglone was shown to increase caspase-3 protein expression." (PMID 39202474, 2024). "In conclusion, our study suggested that PIN1-842G > C (rs2233678) and -667C > T (rs2233679) polymorphisms were significantly associated with the risk of nasopharyngeal cancer in Guangdong Province, and the two SNPs might be a potential biomarker for cancer risk, especially for nasopharyngeal cancer." (PMID 28676695, 2017). "Juglone could also exert cytotoxic effect as a Pin-1 (Peptidyl-prolyl cis/trans isomerase 1) inhibitor through caspase cascade in nasopharyngeal carcinoma, which need further research." (PMID 28388894, 2017). "In nasopharyngeal carcinoma (NPC), Pin1 inhibition reduced NPC cell proliferation, colony formation and anchorage-independent growth through the decrease of cyclin D1 expression and the activation of caspase-3." (PMID 32258027, 2020). "In previous work, we identified ATF1 Thr184 as its new phosphorylation site, which mediates the interaction between ATF1 and Pin1, enhances ATF1 transcription activity and the development of nasopharyngeal carcinoma." (PMID 35397606, 2022).
triple-negative breast carcinoma (12 papers, 2018 to 2024). An invasive breast carcinoma which is negative for expression of estrogen receptor (ER), progesterone receptor (PR), and human epidermal growth factor receptor 2 (HER2). "In contrast to Ser65 and Ser138, Ser71 phosphorylation by DAPK1 inhibits Pin1 PPIase activity and, subsequently, cellular proliferation in triple-negative breast cancer (TNBC) cells." (PMID 38745861, 2024). "ATRA acts as inhibitor of PIN1, reducing for example in vivo growth of triple-negative breast cancer xenografts by the degradation of PIN1 protein." (PMID 32927768, 2020). "Here, the authors show that this combination has potent anticancer activity in triple negative breast cancer by cooperatively targeting Pin1, a master regulator of oncogenic signaling networks, to eliminate cancer stem cells." (PMID 30093655, 2018). "ATO, at clinically relevant and safe doses, ablates Pin1 to inactivate multiple oncoproteins and activate many tumor suppressors and global microRNAs, as well as inhibit triple-negative breast cancer (TNBC) tumor growth." (PMID 30093655, 2018). "Here, we identify cyclin-dependent kinase 1 (CDK1) and peptidyl-prolyl cis-trans isomerase NIMA-interacting 1 (PIN1) as two previously uncharacterized regulators of pVHL in multiple types of human cancers harboring wild-type VHL including triple-negative breast cancer (TNBC)." (PMID 36813923, 2023). "As illustrated, Pin1 regulates a substantial range of CDK substrates, including SEPT9 for cytokinesis completion, Smad3 for oncogenesis in CDK triple-negative breast cancer, and even p27, a CDK inhibitor that is regulated by Pin1." (PMID 38727267, 2024). "Ablating Pin1 enzymatic activity with Sulfopin, a selective Pin1 inhibitor, was successful at blocking MYC-driven tumors like pancreatic ductal adenocarcinoma (PDAC) and triple-negative breast cancer, in vitro and in vivo." (PMID 38745861, 2024). "While, all-trans retinoic acid (ATRA), the active metabolite of vitamin A and the downstream bio-product of RETSAT, has recently been used to inhibit and degrade Pin1, leading to reduced APL and triple negative breast cancer growth." (PMID 34805153, 2021). "ATRA was capable of decreasing Pin1 and tumor growth in APL mouse models and APL human patients’ bone marrow, along with in vivo models of triple negative breast cancer and acute myeloid leukemia; both cancers overexpress Pin1." (PMID 33322239, 2020).
colorectal cancer (11 papers, 2011 to 2025). A primary or metastatic malignant neoplasm that affects the colon or rectum. "studies on brain samples from individuals with mild cognitive impairment and AD have demonstrated significantly reduced levels of PIN1 expression, while PIN1 is typically overexpressed in various human cancers, such as colorectal cancer." (PMID 38250575, 2023). "CNOT2, MID1IP1, and Pin1 genes are overexpressed in cancer cells of various organs, such as colorectal cancer and liver cancer, promoting tumor growth and metastasis, and commonly regulating the expression of c-Myc." (PMID 36569330, 2022). "In human colorectal cancer, the expression of cytoplasmic Pin1 is importantly correlated with aggressive tumor behaviors and a worse prognosis in colorectal cancer." (PMID 32258027, 2020). "To investigate whether inhibition of Pin1 prevents CRC cell growth, we performed western blot analysis to measure expression of Pin1 in five representative colorectal cancer cell lines, namely, Caco-2, HCT116, HT29, SW480, and DLD-1." (PMID 35433695, 2022). "Although chemical inhibitors of Pin1 show potent antitumor therapeutic properties against various cancers, their effect on colorectal cancer, especially colorectal tumor-initiating cells, remains unknown." (PMID 35433695, 2022). "Although studies show that high Pin1 expression is associated with progression of human CRC, no study has examined the effect of the Pin1 protein on the tumorigenicity of tumor-initiating colorectal cancer cells." (PMID 35433695, 2022). "In human colorectal cancer, it has been found that both Pin1 and Nanog are located in the perinuclear space in the cytoplasm where they may interact to affect cell proliferation and maintain the stemness of human colorectal cancer." (PMID 23708493, 2013). "The utility of PIN1 gene may be - in future - very crucial for diagnostics and treatment of thyroid cancer (especially of PTC), based on the facts that overexpression of Pin1 has been found to be an excellent prognostic marker in some other human cancers (e.g., prostate, breast, colorectal cancers)." (PMID 21219594, 2011). "Although these results support the concept that Pin1 promotes cancer progression, and that Juglone and KPT6566 suppress the tumorigenic potential of colorectal cancer, it remains unclear whether Pin1 inhibitors have similar effects on other solid tumors." (PMID 35433695, 2022).
Parkinson disease (11 papers, 2008 to 2025). A progressive degenerative disorder of the central nervous system characterized by loss of dopamine producing neurons in the substantia nigra and the presence of Lewy bodies in the substantia nigra and locus coeruleus. "Subsequent studies using mice models also demonstrated that Pin1 plays a role in the apoptotic pathway, as Pin1 knockdown cells treated with the Parkinsonism- and apoptosis-inducing drug 1-Methyl-4-phenylpyridinium (MPP+) showed reduced caspase activation." (PMID 36111342, 2022). "For example, in Parkinson's disease (PD) and Huntington's disease (HD), Pin1 is a pro-apoptotic factor in the process of neuronal degeneration, and high levels of Pin1 expression have been found in the brain tissue of patients 75-78." (PMID 33537091, 2021). "In this context, in Parkinson’s disease Pin1 has been shown to regulate alpha-synuclein aggregation by modifying the activity of the alpha-synuclein binding partner synphilin." (PMID 27199664, 2016). "For example, increased levels of Pin1 mRNA and protein may be an important neurotoxic event in the process of Parkinson disease (PD)." (PMID 29403356, 2017). "Furthermore, in Parkinson’s disease Pin1 facilitates formation of alpha-synuclein inclusions by regulating its binding partner synphilin." (PMID 27199664, 2016). "Pin1 is involved in the pathogenesis of certain cancers and protein folding pathologies, in particular aberrant Amyloid processing and Tau hyperphosphorylation like Alzheimer’s and Parkinson’s disease." (PMID 25925689, 2015). "The parvulin-type peptidyl-prolyl cis/trans isomerase Pin1 is subject of intense biochemical and clinical research as it seems to be involved in the pathogenesis of certain cancers and protein folding illnesses like Alzheimer’s and Parkinson’s disease." (PMID 19787094, 2008). "PIN1 is widely expressed in the central and peripheral nervous system regions and is involved in the regulation of neuronal development, apoptosis, and synaptic activity; it plays an important role in many neurodegenerative disorders, such as Alzheimer’s disease (AD) and Parkinson’s disease (PD)." (PMID 40309848, 2025). "In contrast with Pin1 neuroprotective role in AD, Pin1 has been found to accumulate in the Lewy bodies of human PD (Parkinson disease) brains and to contribute to the formation of α-synuclein inclusions." (PMID 33083964, 2021). "This scenario would not be that unlikely as it has been already described in Parkinson's disease where synphilin-1 plays the intermediate role between PIN1 and α-synuclein." (PMID 28533744, 2017).
tauopathy (11 papers, 2009 to 2024). Neurodegenerative disorders involving deposition of abnormal tau protein isoforms (tau proteins) in neurons and glial cells in the brain. "Pin1 was shown to bind to phosphorylated Thr-668, which is important since knockout of Pin1 causes tauopathy and neurodegeneration and Pin1 is downregulated in AD neurons." (PMID 19602287, 2009). "This neuroprotective role of Pin1 is exemplified in gene manipulation studies, wherein Pin1 knockout induced tauopathy and increased tau stability in murine models while Pin1 overexpression suppressed tauopathic phenotypes." (PMID 38727267, 2024). "Conversely, Pin1 overexpression reduces tau levels and suppresses the tauopathy phenotype in transgenic mice expressing wild-type tau." (PMID 19284597, 2009). "We also highlighted the novel role of the Pin1-cis P-tau-ApoE axis in the development of preE, and propagation of cis P-tau-mediated abnormal protein aggregation (tauopathy) from the placenta to cerebral tissues later in life, leading to neurodegenerative conditions." (PMID 39857613, 2024). "This review highlights the novel role of the Pin1-cis P-tau axis, and to a lesser extent ApoE, in the development of preeclampsia and propagation of cis P-tau-mediated tauopathy from the placenta to cerebral tissues in the long term, leading to dementia similar to other neurodegenerative conditions." (PMID 39857613, 2024). "Pin1 was shown to be involved in tauopathies since Pin1 dysfunction may have critical consequences on tau pathological aggregation and neuronal death." (PMID 24646911, 2014). "Moreover, when Pin1-/- mice are crossed with transgenic mice overexpressing mutant (P301L) tau, P301L mutant tau levels are decreased and the robust tauopathy phenotype is abolished." (PMID 19284597, 2009). "However, in keeping with the opposing effects of Pin1 on wild-type tau and P301L-tau in SH-SY5Y cells, Pin1 overexpression exacerbates the tauopathy phenotype in P301L tau transgenic mice." (PMID 19284597, 2009). "Such Pin1 inhibitors that reduce Pin activity would not be directly applicable to treat AD because Pin1 deficiency contributes to AD, and Pin1 expression is inversely correlated with tauopathy and AD." (PMID 31884567, 2020). "Overexpressing Pin1 or preventing Pin1 inhibition might be a new approach to block tauopathy." (PMID 25031641, 2014).
acute myeloid leukemia (10 papers, 2015 to 2024). Acute myeloid leukemia (AML) is a group of neoplasms arising from precursor cells committed to the myeloid cell-line differentiation. "The first PROTAC degrader of Pin1 was developed and exhibited potent degradation-dependent anti-proliferative activities in acute myeloid leukemia cells." (PMID 38550694, 2024). "Significantly, this PROTAC degrader exhibited potent cell growth inhibition against a panel of acute myeloid leukemia (AML) cell lines which was degradation-dependent, with Pin1 inhibitor Sulfopin showing no activity." (PMID 38550694, 2024). "Here, we report the discovery of P1D-34, a first-in-class and potent PROTAC degrader of Pin1, which induced Pin1 degradation with a DC50 value of 177 nM and exhibited potent degradation-dependent anti-proliferative activities in a panel of acute myeloid leukemia (AML) cell lines." (PMID 38550694, 2024).
Cognitive impairment (10 papers, 2016 to 2025). Abnormal cognition is characterized by deficits in thinking, reasoning, or remembering. "Besides, studies have revealed that polymorphisms of the PIN-1 gene may affect neurodegeneration in the hippocampal area, which may lead to mild cognitive impairment and eventually AD." (PMID 27920753, 2016). "These recent advances have revealed the exciting novel role of the Pin1-cis P-tau axis in the development and treatment of vascular contribution to cognitive impairment and dementia and preeclampsia." (PMID 38628595, 2024). "However, a compensatory activation or upregulation of Pin1 has been found in mild cognitive impairment, critically indicating that Pin1-based therapeutics needs to be considered depending on the course of AD." (PMID 31884567, 2020). "Elderly Pin1 KO mice develop a complex phenotype of premature aging characteristics: namely, reduced body size, telomere instability, decreased germ-cell proliferation rate, cognitive impairment and neuronal degeneration that resembles human AD." (PMID 30096758, 2018). "Indeed, Pin1 KO mice develop a complex phenotype of premature aging, cognitive impairment in elderly mice and neuronal degeneration resembling that of the AD in humans." (PMID 30096758, 2018). "With aging, the activity of Pin1 protein may be lost by oxidation in mild cognitive impairment, which could lead to the formation of Aβ plaques and hyperphosphorylated Tau in preclinical stages of AD." (PMID 28458925, 2017). "Therefore, modulating the expression of PIN1 may be a potential therapeutic strategy for improving cognitive impairment and related neurological disorders." (PMID 40309848, 2025).
liver cancer (10 papers, 2007 to 2023). An epithelial or non-epithelial malignant neoplasm that arises from the liver. "Genetic knockdown of Pin1 reduces tumour growth and metastasis in many cancers, such as breast, lung and liver cancer." (PMID 32010480, 2020). "It has been reported that the expression of GSTP1 is decreased after treatment with the Pin1 inhibitor ATRA in the liver cancer cell line PLC/Huh-7." (PMID 32010480, 2020). "Pin1 overexpression is prevalent in human cancers, including liver cancer, and upregulation of Nek6 mRNA was found to correlate with Pin1 upregulation in 70% of hepatic cell carcinomas." (PMID 17727698, 2007). "ATRA binds, inhibits, and induces Pin1 degradation, thereby exerting anticancer activity against APL, AML, and breast and liver cancer by blocking multiple cancer pathways." (PMID 30093655, 2018).
Obesity (10 papers, 2012 to 2024). Accumulation of substantial excess body fat. "Deficiency of Pin1 in adipocytes protects against obesity, hepatic steatosis, and insulin resistance." (PMID 39351529, 2024). "Pin1 acts as a key regulator of the insulin signaling pathway, and Pin1 knockout mouse models exhibit resistance to fatty diet-induced obesity, highlighting the important role of Pin1 in adipogenesis and obesity." (PMID 39125345, 2024). "Adipocyte-specific Pin1 KO (adipo-Pin1 KO) promotes thermogenesis, resists high-fat diet-induced obesity, and improves glucose tolerance." (PMID 39351529, 2024). "Pin1 is upregulated in malignant tumors, hepatitis, and metabolic syndrome-related diseases such as obesity and diabetes and has been reported to be involved in promoting the pathogenesis of these diseases." (PMID 36393854, 2022). "Pin1 expression in adipose tissue is markedly increased by obesity." (PMID 39351529, 2024). "As a result, Pin1 KO mice are highly resistant to diet-induced obesity." (PMID 39351529, 2024). "Interestingly, adipocyte-specific Pin1 KO mice show an alleviation of both HFD-induced obesity and fatty liver development, indicating the amelioration of obesity to be linked to the prevention of NASH." (PMID 31795496, 2019). "Therefore, Pin1 KO mice were resistant to high-fat-diet (HFD) induced obesity, with the activity level of AMPK in muscle significantly higher than in WT mice." (PMID 30096758, 2018). "In addition, since the molecule modulates glucose homeostasis in the brain and peripherally, Pin1 KO mice are resistant to diet-induced obesity, insulin resistance, peripheral glucose intolerance and diabetic vascular dysfunction." (PMID 30096758, 2018). "Pin1 is thus a potential target for treatments of obesity and sarcopenia as well as cancers." (PMID 27618008, 2016). "Consistent with the in vitro data, Pin1 KO mice show resistance to HFD-induced obesity." (PMID 27618008, 2016). "Importantly, Pin1 KO mice were shown to be highly resistant to the development of obesity and NASH." (PMID 37240193, 2023). "Recent studies including ours have obtained evidence indicating that Pin1 is involved in a wide range of diseases, such as diabetes, non-alcoholic steatohepatitis (NASH), obesity, osteoporosis and cardiac hypertrophy." (PMID 27618008, 2016). "Interestingly, while Pin1 expression is markedly increased by high-fat diet feeding, Pin1 KO mice are resistant to diet-induced obesity, non-alcoholic steatohepatitis and diabetic vascular dysfunction." (PMID 27618008, 2016).